SMURF2P1 (SMAD specific E3 ubiquitin protein ligase 2 pseudogene 1)
Gene: Transcribed unprocessed pseudogene on chromosome 17 (30,600,865 to 30,615,980, forward strand). Ensembl gene ENSG00000248121.
Diseases named in the same sentence as SMURF2P1 in open-access papers:
SMURF2P1 is named in the same sentence as 2 diseases in open-access papers, as found by Europe PMC text mining. Sharing a sentence is not in itself a finding about the gene and the disease. The quoted sentences say what the papers report.
cervical adenocarcinoma (1 paper, 2022). An adenocarcinoma arising from the cervical epithelium. "Combined with the results of qRT-PCR, we found that SMURF2P1 belonged to the onco-stimulating gene and might have a greater role in the development of cervical adenocarcinoma." (PMID 36408157, 2022). "According to the experimental validation, we found that SMURF2P1 belongs to the co-stimulatory genes and might assume greater importance in the development of cervical adenocarcinoma." (PMID 36408157, 2022).
SMURF2P1 also shares sentences with these, for which no sentence is quoted: cancer (1 paper).